SOCS3 (suppressor of cytokine signaling 3)
Diseases named in the same sentence as SOCS3 in open-access papers (continued):
Sharing a sentence is not in itself a finding about the gene and the disease.
pulmonary TB (3 papers, 2015 to 2022). "They concluded that high SOCS3 expression is a factor in the impaired T cell function of pulmonary TB patients." (PMID 35419455, 2022). "Humoral immunity is also stimulated at the site of disease: pulmonary TB is associated with an increase in the Th2 cytokines IL-4, CCL-4 and SOCS3 in bronchoalveolar lavage (BAL) fluid taken from patients with active pulmonary TB." (PMID 27865379, 2016). "While we could not detect SOCS-1 mRNA in PBMCs, confirming a previous report from our group, we report increased mRNA expression of SOCS-3 in PBMCs from pulmonary TB patients when compared to PBMCs from healthy controls." (PMID 25887604, 2015).
sarcoma (3 papers, 2021 to 2024). A usually aggressive malignant neoplasm of the soft tissue or bone. "T‐cells in the sarcoma microenvironment exhibited elevated levels of cytotoxicity (GZMB, GNLY and KLRD1), exhaustion (HAVCR2, CD38, CD160, CXCL13 and CX3CR1), and inflammation (IL33, PPARG, IL6R and SOCS3), suggesting an activated but exhausted phenotype." (PMID 39658531, 2024).
skin cancer (3 papers, 2017 to 2022). "RUNX1 maintains the active/phosphorylated form of the oncogene STAT3 by inhibiting SOCS3/4 in skin cancer, thereby increasing cell survival, proliferation, and invasion." (PMID 36551618, 2022). "As a whole, these data provides the rationale for the use in BCC and SCC skin tumors of SOCS3 mimetics, being able to inhibit the deleterious effects of IL-22 in these contexts." (PMID 28445952, 2017). "Next, we analyzed SOCS3 and SOCS1 levels in SCC and BCC skin tumor lines left untreated or stimulated with IL-22." (PMID 28445952, 2017). "In both skin tumors, SOCS3 was not detectable in immune cells infiltrating the dermis." (PMID 28445952, 2017). "To this end, we analyzed the in vivo expression of SOCS3 and SOCS1 in BCC or SCC skin tumor specimens, including lesional (LS) and non-lesional (NLS) zones." (PMID 28445952, 2017).
systemic sclerosis (3 papers, 2022 to 2025). A chronic disorder, possibly autoimmune, marked by excessive production of collagen which results in hardening and thickening of body tissues. "The DNMT3A-induced silencing of SOCS3 expression stimulates TGF-β-dependent fibroblast activation in experimental systemic sclerosis (SSc) murine models." (PMID 37189665, 2023). "Interestingly, in fibrotic skin of patients with systemic sclerosis, TGF-β downregulates the expression of SOCS3, which results in activation of STAT3." (PMID 34941574, 2022).
T cell lymphoma (3 papers, 2010 to 2017). "Increasing evidences suggest that deregulation of signal transducer and activator of transcription-3 (STAT3) and suppressor of cytokine signaling 3 (SOCS3) is associated with the pathogenesis of T-cell lymphomas." (PMID 27275540, 2017). "It was worth mentioning that Fisher's exact probability test of the immunochemical results showed both p-STAT3 and SOCS3 protein expression were positively correlated with GLI1 in T-cell lymphomas with each P value<0.05." (PMID 27275540, 2017). "Analysis results showed that both p-STAT3 and SOCS3 protein expression were positively correlated with GLI1 in T-cell lymphomas with the P value as 0.06 and 0.021 respectively." (PMID 27275540, 2017). "We found that protein expressions of GL11, p-STAT3, STAT3, and SOCS3 were up-regulated in T-cell lymphoma tissues and cell lines." (PMID 27275540, 2017). "We examined the expression of GLI1, p-STAT3, STAT3 and SOCS3 for tissues from 35 cases of T-cell lymphomas by immunohistochemistry, in comparation with the control of 15 cases of reactive hyperplasia of lymph node (RHL)." (PMID 27275540, 2017). "Our study results showed that protein expressions of GL11, p-STAT3, STAT3, and SOCS3 were up-regulated both in T-cell lymphoma tissues and T-cell lines." (PMID 27275540, 2017). "In order to explore the potential connections between Hh/GLI1 and STAT3/SOCS3 pathways in T-cell lymphomas, those immunohistochemical results were incorporated into the Fisher's exact probability test." (PMID 27275540, 2017). "Firstly, there is negative-feedback between STAT3 and SOCS3, so aberrantly activated STAT3 stimulate the expression of SOCS3 in T-cell lymphoma." (PMID 27275540, 2017). "In our study, STAT3 and SOCS3 expression was simultaneously increased in T-cell lymphoma." (PMID 27275540, 2017). "We speculated that activation of GLI1 could activate p-STAT3 and SOCS3 expression directly or indirectly, and thereby activated Hh signaling resulting in T-cell lymphoma cell ontogeny." (PMID 27275540, 2017). "This study mainly focuses on the Hh/GLI1 and STAT3/SOCS3 pathways in T-cell lymphomas." (PMID 27275540, 2017). "Moreover, the protein expressions of p-STAT3 and SOCS3 were positively correlated with GLI1 in T-cell lymphomas." (PMID 27275540, 2017). "Secondly, SOCS3 may play an oncogenic role in T-cell lymphoma by inhibiting differentiation and apoptosis signals arising from specific cytokines." (PMID 27275540, 2017). "The expressions of GLI1, p-STAT3, STAT3, and SOCS3 were detected respectively in 28/35(80.0%), 26/35(74.2%), 32/35(91.4%), and 24/35(68.6%) of T-cell lymphoma cases, when tumors displaying staining in 30% or more of the cells were categorized as positive cases." (PMID 27275540, 2017). "Although SOCS3 was described as a negative regulator of STAT3 in many malignancies, the exact role of SOCS3 in T-cell lymphoma was largely unknown." (PMID 27275540, 2017).
thyroid cancer (3 papers, 2016 to 2024). "This is the first report on 15d-PGJ2-induced SOCS3 expression, which evidences a novel therapeutic option for the treatment of thyroid cancer and other cancers that are dependent on IL-6 signaling." (PMID 27190500, 2016).
toxoplasmosis (3 papers, 2017 to 2024). A parasitic disease contracted by the ingestion or fetal transmission of toxoplasma gondii. "It was shown during experimental toxoplasmosis that supplementation with recombinant IL-12 corrects the susceptible phenotype in macrophage-specific SOCS3-deficient animals." (PMID 29176982, 2017). "The depletion of SOCS3 resulted in elevated T. gondii-induced STAT3 signaling, and macrophages and neutrophils with SOCS3 deletion had reduced levels of IL-12 and IFN-γ and succumbed to toxoplasmosis." (PMID 38297164, 2024).
Abdominal obesity (2 papers, 2018 to 2022). Excessive fat around the stomach and abdomen. "This study was conducted to evaluate the potential causality association of SOCS3 methylation with abdominal obesity using Mendelian randomization." (PMID 36145200, 2022). "The current research demonstrated that 5 CpG sites methylation levels of SOCS3 were inversely associated with abdominal obesity, and methylation levels of 18 CpG sites were positively associated with abdominal obesity." (PMID 36145200, 2022). "In this study, the causal association between the methylation levels of SOCS3 and abdominal obesity was established and some novelty sites for the association were found." (PMID 36145200, 2022). "To date, studies involved in the association of SOCS3 methylation with abdominal obesity have been limited, especially those conducted to infer the etiology of this association in an observational study." (PMID 36145200, 2022). "The purpose of this study was to evaluate the association between SOCS3 methylation and abdominal obesity." (PMID 36145200, 2022). "The causality was found between the SOCS3 methylation level and abdominal obesity in the Chinese population." (PMID 36145200, 2022). "Furthermore, the Mendelian-randomization analyses indicated a causal association between SOCS3 methylation levels and abdominal obesity." (PMID 36145200, 2022). "However, the reports on exploring the associations between SOCS3 methylation levels and abdominal obesity (defined by WC) are limited." (PMID 36145200, 2022). "In addition, the association between SOCS3 methylation level and abdominal obesity was found only in the Chinese rural population, so caution should be taken when generalizing the findings to other populations." (PMID 36145200, 2022). "The potential mechanisms responsible for the association of SOCS3 methylation levels with abdominal obesity may be elucidated by the following information." (PMID 36145200, 2022). "The causal relationship between SOCS3 methylation and abdominal obesity was found using the maximum-likelihood method and Mendelian randomization method of penalized inverse variance weighted (MR-IVW), and the β values (95% CI) were 5.342 (0.215, 10.469) and 4.911 (0.259, 9.564), respectively." (PMID 36145200, 2022). "Furthermore, we conducted Mendelian randomization studies to explore whether there was causality between SOCS3 methylation levels and abdominal obesity by using the SNP of SOCS3 as instrumental variables." (PMID 36145200, 2022). "The logistic regression was used to assess the relationship of SOCS3 methylation level and SNP genotyping with abdominal obesity." (PMID 36145200, 2022). "The current study provided evidence in support of the causal associations of the SOCS3 methylation level with abdominal obesity in the Chinese rural population, which suggested that SOCS3 methylation might be potentially used as a marker for development of abdominal obesity." (PMID 36145200, 2022). "It is necessary to explore the relationship between DNA methylation of SOCS3 and abdominal obesity in multicenter studies." (PMID 36145200, 2022). "The dose–response relationships between SOCS3 methylation levels and abdominal obesity were linear." (PMID 36145200, 2022).
adenomyosis (2 papers, 2020 to 2025). The growth of endometrial tissue inside the muscular wall of the uterine corpus. "Isolated total RNA from endometrial biopsy samples collected during the window of receptivity were used to verify whether selected candidate genes LIF, SOCS3, FOS, JUNB, IL6 and IL10 were differentially expressed between adenomyosis and control groups." (PMID 32933042, 2020). "Despite LIF, IL6, IL10, JUNB, FOS and SOCS3 showing no statistically altered expression patterns between study groups, their lower expression levels were observed in the adenomyosis group." (PMID 32933042, 2020). "Although we did not detect sustained Stat3 mRNA elevation—likely due to negative feedback by SOCS3 —the persistent Il6 mRNA overexpression suggests that post-transcriptional activation of STAT3 or alternative pathways (e.g. MAPK) may underlie lesion progression in adenomyosis." (PMID 41298316, 2025).
anaplastic large cell lymphoma (2 papers, 2007 to 2014). Anaplastic large cell lymphoma (ALCL) is a rare and aggressive peripheral T-cell non-Hodgkin lymphoma, belonging to the group of CD30-positive lymphoproliferative disorders, which affects lymph nodes and extranodal sites. "Over expression of suppressor of cytokine signaling 3 is associated with anaplastic large cell lymphoma." (PMID 17316436, 2007).
anemia (2 papers, 2012 to 2023). A reduction in the number of red blood cells, the amount of hemoglobin, and/or the volume of packed red blood cells. "Anemia was associated with OAS1 and CTLA4 gene polymorphisms (p = 0.049 and p = 0.045, respectively), neutropenia and thromobocytopenia were associated with SOCS3 gene polymorphism (p = 0.02 and p = 0.002, respectively)." (PMID 23133602, 2012). "Anemia was associated with the OAS1 rs2660 and the CTL4 rs231775 polymorphisms, and neutropenia and thrombocytopenia were associated with the polymorphism rs4969170 in the SOCS3 gene." (PMID 23133602, 2012).
aneurysm (2 papers, 2019 to 2020). Bulging or ballooning in an area of an artery secondary to arterial wall weakening. "A relevant study showed that overexpression of SOCS3 in bone marrow-derived cells significantly increased aneurysm severity (P = 0.04) demonstrating that STAT3/SOCS3 signaling in bone marrow-derived cells contributes to AAA development." (PMID 33415145, 2020).
Aortic dissection (2 papers, 2022 to 2023). Aortic dissection refers to a tear in the intimal layer of the aorta causing a separation between the intima and the medial layers of the aorta. "Suppressor of cytokine signaling 3 (SOCS3) is a more recent gene to be implicated in the pathogenesis of aortic dissections." (PMID 36561772, 2022). "In a recent study, SMC-specific SOCS3 deletion was protective against aortic dissection." (PMID 37008329, 2023).
atopic asthma (2 papers, 2015 to 2021). An asthma that is characterized by symptoms that are triggered by an allergic reaction caused by inhaled allergens such as dust mite allergen, pet dander, pollen and mold. "We next investigated the abundance of SOCS1 and SOCS3 proteins in biopsy specimens of adults with uninfected mild-to-moderate atopic asthma (AA) compared with nonatopic nonasthmatic (NANA) adult control donors." (PMID 25630941, 2015).
autism (2 papers, 2025). Persistent deficits in social interaction and communication and interaction as well as a markedly restricted repertoire of activity and interest as well as repetitive patterns of behavior. "In support, others have shown that the recruitment of Dnmts by MALAT1 hypermethylated the DNA of suppressor of cytokine signaling 3 in the Parkinson’s disease model and CASP3 in the autism model." (PMID 40650203, 2025).
bone inflammatory diseases (2 papers, 2013 to 2014). "Our findings implicate SOCS3 as an important regulatory mediator in bone inflammatory diseases by targeting MMP-13." (PMID 23638389, 2013). "Thus, the role of SOCS3 during bone inflammation is complex; more details of the SOCS3 pathway are necessary for a better understanding of the mechanisms of various bone inflammatory diseases." (PMID 24454312, 2014). "However, due to the embryonic lethality of SOCS3 knockout mice, the role of SOCS3 in inflammatory bone diseases remains to be determined." (PMID 23638389, 2013). "However, the expression of SOCS3 in these cells in response to various inflammatory stimuli and its function in bone inflammatory diseases are still largely unknown." (PMID 24454312, 2014).
breast tumors (2 papers, 2010 to 2020). "In breast tumour cells, it has been postulated that the IFNγ induced anti-proliferative effects are reduced due to a lower sensitivity to SOCS3 induction." (PMID 20553623, 2010). "Hence, low SOCS3 expression is a probable factor in the enhanced IDO1 expression seen in TN breast tumors." (PMID 33109232, 2020).
cholestasis (2 papers, 2017 to 2023). Impairment of the bile flow caused by obstruction within the liver, or outside the liver in the bile duct system. "GW4064 treatment in the PNAC mouse increased hepatic FXR binding to the Stat3 promoter, further increased STAT3 phosphorylation and upregulated Socs1 and Socs3 mRNA, and prevented cholestasis." (PMID 36848082, 2023). "Although it cannot be ruled out that SOCS3 had a similar function as SOCS1, the unrecovered status of cholestasis provides a possible explanation." (PMID 28842621, 2017).
chronic asthma (2 papers, 2014 to 2023). An asthma that is characterized by the development of persistent airway inflammation and recurrent attacks of breathlessness and wheezing, which vary in severity and frequency. "In conclusion, we have demonstrated using different in vitro and in vivo techniques that SOCS3-siRNA intranasal delivered in a chronic asthma mouse model leads to inhibited asthmatic responses." (PMID 24637581, 2014). "Indeed, SOCS3 levels were reduced in a murine model of chronic asthma and macrophage-derived EVs enriched in SOCS3 inhibited the activation of transcription in epithelial cells challenged with IL-4/IL-13." (PMID 36902079, 2023). "Therefore, we have developed a therapeutic approach in a murine model of chronic asthma by delivering SOCS3-siRNA intranasally." (PMID 24637581, 2014).
chronic obstructive airway disease (2 papers, 2013 to 2019). "The inhibition of SOCS3 mRNA expression is related to the imbalance of cytokine signaling observed in the bronchial epithelium of patients with chronic obstructive airway disease." (PMID 31318922, 2019). "The inhibition of cytokine signaling via the action of SOCS may also play an important role in the pathophysiology of chronic obstructive airway diseases and a study has shown that SOCS-3 regulates the onset and maintenance of TH2-mediated responses in bronchial asthma." (PMID 24138793, 2013). "Since chronic obstructive pulmonary disease (COPD) is also characterized by inflammatory changes and airflow limitation, the present study assessed the transcriptional expression of SOCS-3 in COPD." (PMID 24138793, 2013).
colorectal adenoma (2 papers, 2010 to 2015). An adenoma that arises from the colon or rectum. "Low SOCS3 mRNA expression is not an independent biomarker of colorectal adenoma risk in the normal mucosa." (PMID 20500855, 2010). "However, our study found that low or silenced SOCS3 expression does not occur in the normal mucosa of patients with colorectal adenoma." (PMID 20500855, 2010).
coronary artery disease (2 papers, 2019 to 2021). "Increased SOCS3 expression has been found associated with RA, coronary artery disease, and PD." (PMID 35153741, 2021).
cutaneous melanoma (2 papers, 2021 to 2022). A primary melanoma arising from atypical melanocytes in the skin. "In humans, analyses of the TCGA dataset revealed positive mRNA correlations from cutaneous melanoma biopsies for expression of NLRP3 and IL‐6 (p=4.86e-20), IL‐6 and the STAT3 target gene Socs3 (p=1.82e-62), IL-1β and Socs3 (p=1.71e-31)." (PMID 34531850, 2021).